NEUROD1 (neuronal differentiation 1)
Description:
Acts as a transcriptional activator: mediates transcriptional activation by binding to E box-containing promoter consensus core sequences 5'-CANNTG-3'. Associates with the p300/CBP transcription coactivator complex to stimulate transcription of the secretin gene as well as the gene encoding the cyclin-dependent kinase inhibitor CDKN1A. Contributes to the regulation of several cell differentiation pathways, like those that promote the formation of early retinal ganglion cells, inner ear sensory neurons, granule cells forming either the cerebellum or the dentate gyrus cell layer of the hippocampus, endocrine islet cells of the pancreas and enteroendocrine cells of the small intestine. Together with PAX6 or SIX3, is required for the regulation of amacrine cell fate specification. Also required for dendrite morphogenesis and maintenance in the cerebellar cortex. Associates with chromatin to enhancer regulatory elements in genes encoding key transcriptional regulators of neurogenesis (By similarity).
Synonyms: NeuroD; bHLHa3; BETA2; BHF-1; MODY6; T2D
Tractability: No criterion of Open Targets' tractability assessment is met for any kind of drug.
Gene: Protein-coding gene on chromosome 2 (181,668,295 to 181,680,827, reverse strand). Ensembl gene ENSG00000162992.
Subcellular location: Cytoplasm; Nucleus
Pathways (Reactome):
Developmental Biology: Regulation of gene expression in beta cells; Regulation of gene expression in endocrine-committed (NEUROG3+) progenitor cells
Gene Ontology:
Molecular function: DNA-binding transcription activator activity, RNA polymerase II-specific; DNA-binding transcription factor activity; E-box binding; protein binding; protein heterodimerization activity; RNA polymerase II-specific DNA-binding transcription factor binding; sequence-specific DNA binding; sequence-specific double-stranded DNA binding; chromatin binding; DNA-binding transcription factor activity, RNA polymerase II-specific; DNA binding; protein dimerization activity; RNA polymerase II cis-regulatory region sequence-specific DNA binding
Biological process: cellular response to glucocorticoid stimulus; insulin secretion; positive regulation of insulin secretion; positive regulation of transcription by RNA polymerase II; response to glucose; amacrine cell differentiation; axon development; cerebellum development; dentate gyrus development; embryonic organ morphogenesis; endocrine pancreas development; enteroendocrine cell differentiation; glucose homeostasis; inner ear development; negative regulation of type B pancreatic cell apoptotic process; neurogenesis; positive regulation of apoptotic process; positive regulation of cell differentiation; positive regulation of DNA-templated transcription; positive regulation of neuron differentiation; regulation of insulin secretion; regulation of intestinal epithelial structure maintenance; sensory organ development; nervous system development; regulation of DNA-templated transcription
Cellular component: nucleus; RNA polymerase II transcription regulator complex; chromatin; nucleoplasm; cytoplasm
Genetic constraint (gnomAD): Loss-of-function variants: 9 observed, 22.84 expected, observed/expected ratio (o/e) 0.39, 90% interval 0.24 to 0.69. The upper end of that interval is the gene's LOEUF score, 0.69, which puts it in group 2 of 6, group 1 being the genes least tolerant of losing a copy. Missense variants: 434 observed, 497.9 expected, observed/expected ratio (o/e) 0.87, 90% interval 0.81 to 0.94. Synonymous variants: 199 observed, 201.01 expected, observed/expected ratio (o/e) 0.99, 90% interval 0.88 to 1.11.
Gene-disease validity (ClinGen):
ClinGen rates the evidence that NEUROD1 causes each of these diseases.
monogenic diabetes (autosomal dominant; autosomal recessive): Moderate. Diabetes mellitus that is caused by mutations in a single gene.
Homologues: Orthologues: macaque NEUROD1 (99% identical), pig NEUROD1 (99% identical), rat Neurod1 (98% identical), mouse Neurod1 (98% identical), guinea pig NEUROD1 (97% identical), tropical clawed frog neurod1 (79% identical), zebrafish neurod1 (76% identical), dog NEUROD1 (41% identical), Caenorhabditis elegans ngn-1 (19% identical), Drosophila melanogaster tap (17% identical), Drosophila melanogaster ato (12% identical), Drosophila melanogaster amos (10% identical), and 1 more. Paralogues in human: NEUROD2 (51% identical), NEUROD4 (50% identical), NEUROD6 (47% identical), NEUROG2 (21% identical), NEUROG1 (19% identical), ATOH1 (18% identical), NEUROG3 (17% identical), OLIG3 (17% identical), BHLHE22 (16% identical), BHLHA15 (15% identical), OLIG2 (15% identical), BHLHE23 (14% identical), and 3 more.
Diseases named in the same sentence as NEUROD1 in open-access papers:
NEUROD1 is named in the same sentence as 125 diseases in open-access papers, as found by Europe PMC text mining. Sharing a sentence is not in itself a finding about the gene and the disease. The quoted sentences say what the papers report.
diabetes (51 papers, 2009 to 2025). "NEUROD1 homozygous mutations are known to induce permanent newborn diabetes mellitus (PNDM), whereas heterozygous mutations can result in NEUROD1‐MODY." (PMID 40148250, 2025). "Several studies have screened NEUROD1 gene mutations in patients with diabetes suspected of having MODY but with a relatively small sample size (varying from 25 to 289)." (PMID 40148250, 2025). "Among these, MODY6, caused by heterozygous mutations in the neurogenic differentiation factor 1 (NEUROD1) gene, is a rare subtype that exhibits considerable phenotypic variability, ranging from mild hyperglycemia to ketosis-prone diabetes." (PMID 41255541, 2025). "A Czech study associated diabetes with a NeuroD1/MODY6 gene mutation in two families, all members of which were obese, with proband displaying elevated fasting C-peptide level." (PMID 38333726, 2023). "NEUROD1 inactivation during the differentiation of human embryonic stem cells causes neonatal diabetes mellitus and defective β-cell function." (PMID 37181651, 2023). "In the context of β-cell identities, Neurod1 deficiency affected numerous genes that serve as markers for β-cell dysfunction and the diabetes-induced dedifferentiation of β-cells." (PMID 37689751, 2023). "Over the next 20 years, NEUROD1 variants have been reported as causative of diabetes in almost 20 families." (PMID 35769090, 2022). "NEUROD1 variant was found in a patient diagnosed with diabetes at 14 and half years, after coincidental findings of hyperglycemia." (PMID 35769090, 2022). "We have documented a new missense mutation (p.Met114Leu c.340A > C) of the NEUROD1 gene, pathogenetic for diabetes mellitus, in a 48 years-old man affected by diabetes since the age of 25 and treated with insulin basal-bolus therapy." (PMID 34654408, 2021). "Of additional interest, the gene Neurod1, which is highly implicated in neuron development and in diabetes, had a strong tendency for differential expression (FDR = 0.058)." (PMID 33239620, 2020). "These include NeuroD1, which regulates both neuronal differentiation as well as insulin expression, and is associated with type 2 diabetes mellitus, an obesity-related complication reported in adults with PWS43,44." (PMID 29691382, 2018). "We excluded the remaining MODY genes (CEL, PDX1, PAX4, BLK, KLF11, NEUROD1) from this analysis since either very few missense mutations in these genes have been associated with early onset diabetes or the genetic evidence for association is limited." (PMID 29207974, 2017). "The basic helix-loop-helix (bHLH) transcription factor NeuroD1 (previously called β2) has roles in pancreas development and islet formation and mutations in this gene have been linked to Type 2 Diabetes mellitus and MODY6." (PMID 25480530, 2014). "NeuroD1-deficiency in mice causes severe diabetes and perinatal lethality because NeuroD1 is required for insulin gene expression." (PMID 22988465, 2012). "Disruption of Neurod1 during pancreatic development causes severe neonatal diabetes; however, the exact role of NEUROD1 in the differentiation programs of endocrine cells is unknown." (PMID 37689751, 2023). "NEUROD1 is highly expressed in neuroendocrine tissues and its central function in their development is evident from the mutations causing ketoacidosis-prone diabetes with microvascular sequelae and neurological abnormalities such as cerebellar hypoplasia, hearing and visual impairments, low IQ." (PMID 37255971, 2023). "NeuroD1 embryonic knockout in C57BL/6 J mice causes lethal neonatal diabetes." (PMID 37181651, 2023). "We have identified NEUROD1 missense mutation (p.Glu59Gln) in one MELAS patient with diabetes." (PMID 33484326, 2021). "Mutations of the Neurod1 gene cause diabetes in humans and mice." (PMID 34201511, 2021).
diabetes (continued). "Examples include as follows: (a) NEUROD1 which encodes a transcription factor that is involved in the development of the endocrine cell lineage and has been implicated in monogenic diabetes, (b) PRKCB involved in insulin resistance and (c) GNAS, implicated in beta-cell proliferation." (PMID 30914061, 2019). "It was found that the expression of NeuroD1-βcellulin reversed diabetes and maintained normoglycaemia, with associated up-regulation of both upstream and downstream β-cell transcription factors, including Pdx1, Pax6, Pax4, Nkx2.2, and Nkx6.1, as seen in the current study." (PMID 27070593, 2016). "STZ treatment also suppressed expression of a wide range of genes linked with key β-cell functions or diabetes development, such as G6pc2, Slc2a2 (Glut2), Slc30a8, Neurod1, Ucn3, Gad1, Isl1, Foxa2, Vdr, Pdx1, Fkbp1b and Abcc8, suggesting global β-cell defects in STZ-treated islets." (PMID 23828045, 2013). "Several studies with small sample sizes (n = 25–289) have screened NEUROD1 variants in selected patients who were suspected of having monogenic diabetes and showed a relatively high prevalence (1.5%–4%), which factually might have overestimated the prevalence of NEUROD1‐MODY." (PMID 40148250, 2025). "Current clinical guidelines for monogenic diabetes typically suggest insulin as the primary treatment for MODY6, based chiefly on observational data from cases with NEUROD1 coding region mutations." (PMID 41255541, 2025). "NEUROD1 is expressed by pancreatic and nervous tissues and is essential for the development of beta cells and diabetes, which have been reported to influence cardiac function, as well as inflammation." (PMID 39187864, 2024). "It has been shown that the loss of MafA is an early indicator of β-cell inactivity due to hyperglycaemia, which precedes the reduction in PDX-1 and NeuroD1 for the development of diabetes." (PMID 38745946, 2024). "Recent studies employing systematic or tissue-specific deletions of the Neurod1 gene have revealed a consistent pattern of neurological abnormalities alongside a severe neonatal diabetes phenotype." (PMID 39105169, 2024). "Previous studies have shown that PDX-1 and NeuroD1 are affected in genotypic animal models of diabetes, and there is also an increase in glucagon and alpha cells in pancreatic islets." (PMID 38745946, 2024). "We have documented a new missense mutation (p.Met114Leu c.340A > C) of the Neurogenic differentiation factor 1 gene (NEUROD1), pathogenetic for diabetes mellitus." (PMID 34654408, 2021). "Given the importance of NEUROD1 in diabetes research, we examined different aspects of NEUROD1 requirements for pancreas development in this study." (PMID 34201511, 2021). "Utilizing NGS based strategy, we have recently reported a wider spectrum of MODY mutations involving NEUROD1 and PDX1 in patients with young onset diabetes (<30years) in India." (PMID 28095440, 2017). "The inhibition of Wnt signaling and NeuroD1 in both neurogenic niches of STZ-induced diabetic animals suggests that the impairment of neurogenesis in diabetes is the result of the inhibition of Wnt signaling." (PMID 26075247, 2015). "Because Wnt3-induced NeuroD1 is a critical factor for neurogenesis and pancreatic development, it is suggested that the cognitive deficit and impairment of insulin secretion in diabetes, AD, and HD are due to the impairment of Wnt3-induced NeruoD1 activity." (PMID 26075247, 2015). "For example, the gene NEUROD1 is ranked 1 when using "diabetes" as the reference term, but ranked 6 when using "glucose uptake" as a reference term." (PMID 19575795, 2009). "Maturity‐onset diabetes of the young resulting from mutations of the NEUROD1 gene (NEUROD1‐MODY) is a rare form of diabetes and has not been well studied." (PMID 40148250, 2025). "NEUROD1 plays a critical role in the functional development of the endocrine pancreas, as Neurod1 gene deletions are postnatally lethal within a few days after birth due to severe diabetes." (PMID 39105169, 2024).
diabetes (continued). "A previous study showed that mice lacking NEUROD1 −/− exhibited serious complications of the pancreas, which causes a decline in beta cells, leading to severe diabetes." (PMID 38274107, 2023). "This explains the connection between the NEUROD1 gene and diabetes." (PMID 38274107, 2023). "NEUROD1, a basic helix–loop–helix (bHLH) transcription factor, is crucial for pancreatic development, as mice with deletions of Neurod1 die perinatally due to severe diabetes." (PMID 34201511, 2021). "The pancreatic islets regulate glucose metabolism through secretion of islet hormones such as insulin and glucagon, and INSM2 is a direct target of Ngn3 and NeuroD1, two crucial transcriptional factors involved in human diabetes and pancreatic islet development." (PMID 32511227, 2020). "Interestingly, mutations in NEUROD1 were associated with T2D, whereas upregulation of RCAN1 was shown to cause hyperinsulinemia, β cell dysfunction, and diabetes." (PMID 31159854, 2019). "NPY expression declines postnatally with β-cell maturation, and its re-emergence in animal models of β-cell dysfunction, for example, in β-cell-specific Neurod1 knockout mice, or during diabetes, is thought to contribute to altered β-cell identity and impaired GSIS." (PMID 30303066, 2018). "Similarly, NeuroD1 haploinsufficiency is linked to MODY6 and adult ablation of NeuroD in β-islet cells results in β-cell dysfunction and diabetes." (PMID 22383890, 2012). "Hereditary forms of diabetes also include rare monogenic variants such as MODY (Maturity-Onset Diabetes of the Young), which follows an autosomal dominant inheritance pattern caused by specific mutations in genes such as HNF4A, GCK, HNF1A, HNF1B, PDX1, and NEUROD1." (PMID 40647303, 2025). "Moreover, mutation in NeuroD1 could lead to the defect in pancreatic B cells and thus promote type 2 diabetes mellitus (T2DM), while patients with NeuroD1 Thr45 polymorphism are more susceptible to T2DM." (PMID 38134213, 2023). "Interestingly, NeuroD1 is known to be expressed in pancreatic β cells and to play an essential role in endocrine pancreatic development, as NeuroD1 KO mice exhibited severe diabetes and died perinatally." (PMID 26075247, 2015). "Since hippocampal neurogenesis is coupled with expression of NeuroD1, the expression (and the secretion) of insulin in newborn neurons via the NeuroD1 transcription factor may be upregulated in a treatment that promotes adult neurogenesis in diabetes patients." (PMID 22988465, 2012). "MAF BZIP Transcription Factor A (MAFA), Neuronal Differentiation 1 (NEUROD1) and NEUROD4 were significantly downregulated (p < 0.05) in the diabetes cohort, suggesting a disruption in the transcriptional regulation of β-cell identity and function." (PMID 40244011, 2025). "It should further be noticed that genes of importance for islet function and diabetes such as PDX1, TCF7L2, FOXA2, FOXO1, NEUROD1 and BACH2 have C1, C3 or both these sites at their ATAC-seq open chromatin regions." (PMID 31123324, 2019). "First, mice lacking Neurod1 during pancreas development die shortly after birth from severe diabetes partly due to a reduced number of endocrine cells, particularly β cells." (PMID 37689751, 2023). "Furthermore, several genes involved in the endocrine specification and diabetes development were significantly downregulated, such as HES1, INSM1, HNF1A, NEUROD1, NGN3, NKX2.2, GIPR, MNX1, PROX1, TCF7L2, and HHEX." (PMID 33473118, 2021). "To date, there were no reports on NEUROD1, INS, BLK and ABCC8 variants in pregnant women with diabetes." (PMID 28095440, 2017). "Take a step further to determine whether the induced IPCs give full scope to normal physiological functions of β islet cells, mMSCs expressing a combination of PDX-1, NeuroD1, and MafA were transplanted into the livers of mice with STZ-induced diabetes." (PMID 22761608, 2012).
diabetes (continued). "However, Neurod1CKO did not survive postnatally due to severe neonatal diabetes, corresponding to the phenotype of the global deletion of Neurod1." (PMID 34201511, 2021). "In several recent large‐scale genomic studies of patients with late adolescence/adult‐onset diabetes, pediatric populations, or early‐onset type 2 diabetes mellitus (EOD), NEUROD1 was not included in the screening gene panel." (PMID 40148250, 2025). "Only p.S274fs carried by one participant was classified as LP (0.009%) and six participants carried P197H, which is controversial in terms of pathogenicity, suggesting that NEUROD1‐MODY is rare in the Chinese general population, although we do not know whether this individual has diabetes or not." (PMID 40148250, 2025). "Moreover, regardless of diabetes status, nuclear ISL1 levels trended with nuclear NEUROD1 but were overall reduced in T1D, suggesting that, despite upregulation, a general impairment of nuclear access, potentially stemming from a reduction in importins, prevents α cell (re)maturation in T1D." (PMID 41026524, 2025).